IL6 (interleukin 6)
Diseases named in the same sentence as IL6 in open-access papers (continued):
Sharing a sentence is not in itself a finding about the gene and the disease.
acute pancreatitis (continued). "Latest research provided novel cellular signal pathway that IL-6 promoted TMEM16A expression via activating IL-6R/STAT3 signal to facilitate pathogenesis of acute pancreatitis." (PMID 33118404, 2020). "A comprehensive systematic review and meta‐analysis of the genetic evidence for acute pancreatitis was conducted, and identified credible associations of SPINK1, ALDH2, IL1B, IL6 and IL18 with the risk of acute pancreatitis." (PMID 32011822, 2020). "In acute pancreatitis, pro-inflammatory cytokines such as Interleukin-1β (IL-1β), IL-6 and tumor necrosis factor-α (TNF-α) are primarily produced within the pancreas and subsequently within distant organs." (PMID 32471279, 2020). "Macrophages are a major source of TNF‐α, IL‐1β, and IL‐6, and high serum levels of these cytokines are consistent with acute pancreatitis disease severity." (PMID 32638512, 2020). "Reactive oxygen species (ROS) mediate expression of inflammatory cytokines such as interleukin-6 (IL-6) which reflects the severity of acute pancreatitis." (PMID 33158207, 2020). "Interleukin-6 significantly improves the predictive value for severe acute pancreatitis but is difficult to detect." (PMID 31046705, 2019). "By activation of the Wnt/β-catenin signal, acute pancreatitis was significantly alleviated, as is evident by the down-regulated inflammatory factors including IL-6/10, TNF, and IL-1β." (PMID 35515912, 2019). "In fact, it was reported that IL-6 levels in the circulation are excellent predictors of the severity of lung injury in the etiology of acute pancreatitis." (PMID 29847178, 2018). "Elevated levels of IL-6 have been observed in patients with acute pancreatitis and are determinants of disease severity." (PMID 29068376, 2017). "Evidences suggest that proinflammatory cytokines, such as IL-1β, TNF-α, and IL-6, act as mediators of acute pancreatitis." (PMID 29068376, 2017). "TNFα, playing a dominating role in severe acute pancreatitis, can trigger expression of other inflammatory cytokines such as IL-1β and IL-6 and aggravates the tissue injury." (PMID 28441432, 2017). "As it is primarily induced by IL-6, high level of hepcidin can be found in patients with acute pancreatitis." (PMID 26345247, 2015). "The role of proinflammatory IL-6 in predicting severity of acute pancreatitis seems much more valuable than TNF-α." (PMID 26199633, 2015). "A large number of studies have already confirmed the role of IL-6 in early and accurate prediction of severity in acute pancreatitis." (PMID 26345247, 2015). "A recent study has reported additional markers for acute pancreatitis, including C-reactive protein, α1-antitrypsin, phospholipase A2, and inflammatory markers such as interleukin-6 (IL-6)." (PMID 26100532, 2015). "In terms of predicting complications, IL-6 was found to be excellent in predicting remote organ failure, which is an integral part of severe acute pancreatitis." (PMID 26345247, 2015). "It was demonstrated that the IL-6 level is increased in the blood of patients with acute pancreatitis (AP)." (PMID 25298618, 2014). "A special role in initiating an inflammatory response in the course of acute pancreatitis was attributed to interleukin-6 (IL-6)." (PMID 25298618, 2014). "Oxidative stress and inflammatory mediators, such as IL-6, play an important role in the pathophysiology of acute pancreatitis." (PMID 25298618, 2014). "In AP patients, IL-6 concentration has been increased rapidly within several tens of hours since the occurrence of acute pancreatitis symptoms." (PMID 25298618, 2014). "Inflammatory cytokines such as interleukin-1β (IL-1β) and interleukin-6 (IL-6) play key roles in acute pancreatitis at the early stage of HTAP." (PMID 25365448, 2014). "The role of the proinflammatory IL-8 in prediction of severity of acute pancreatitis seems less valuable than IL-6." (PMID 23476635, 2013).
acute pancreatitis (continued). "Taken together, BAFF as well as IL-6 best distinct between severe cases of acute pancreatitis (sNPoD) and less severe courses of disease (NP or EP), regardless if necrotizing or not." (PMID 23342125, 2013). "With respect to BAFF serum levels, this is the first study to show a role for BAFF in acute inflammation as an acute phase reactant and its predictive value in acute pancreatitis, which outperforms established parameters like IL-6, PCT, and leucocyte counts." (PMID 23342125, 2013). "Serum BAFF correlates with CRP, an established marker of severity in acute pancreatitis at day of admission with a timecourse profil similar to IL-6 over the first nine days." (PMID 23342125, 2013). "In summary, BAFF behaves like an acute phase reactant and outperforms established markers of inflammation in acute pancreatitis, like IL-6 and PCT underscoring the role of BAFF in the acute inflammatory response." (PMID 23342125, 2013). "BAFF outperforms established markers in acute pancreatitis, like IL-6 and PCT underscoring the important role of BAFF in the acute inflammatory response." (PMID 23342125, 2013). "IL-6 is an important inflammatory mediator, which has been reported useful as a severity predictor in acute pancreatitis." (PMID 23110041, 2012). "Other metabolic/biochemical effects of D components have also been reported, for instance, the protective effects on acute pancreatitis in rats through IL-6 reduction, as well as the suppression of reactive oxygen species, nitric oxide and lipid oxidation." (PMID 20979644, 2010). "Serum interleukin-6 is a very reliable marker of necrosis in the first 48 hours of acute biliary pancreatitis." (PMID 19636174, 2009). "The study concluded that serum interleukin-6 is a very reliable marker of necrosis in the first 48 hours of acute biliary pancreatitis." (PMID 19636174, 2009). "Stimulation of production of either acute phase proteins and adhesion molecules or several inflammatory cytokines, including TNF-α, IL-1β and IL-6, occurs after NF-κB activation in acute pancreatitis." (PMID 15987389, 2005). "ROS produced by acute pancreatitis stimulate NF-κB, leading to excessive release of cytokines such as interleukin-1β (IL-1β), interleukin-2 (IL-2), interleukin-18 (IL-18), interleukin-6 (IL-6), and TNF-α." (PMID 40411704, 2025). "Persistent activation of PSCs by cytokines during acute pancreatitis such as TNF-α, IL-1, IL-6, and IL-10, may be a factor involved in the progression from acute pancreatitis to chronic pancreatic injury and fibrosis." (PMID 39759120, 2025). "At this point, it would be interesting to also investigate IL-6-mediated T cell activation in a severe model of acute pancreatitis and evaluate whether similar effects can be observed." (PMID 40560328, 2025). "In the progression of acute pancreatitis, inflammatory factors such as IL-6 and TNF-α drive neutrophil aggregation and release extracellular traps (NETs), exacerbating tissue damage, while inducing lymphocyte apoptosis (especially CD4+ T cells), leading to immune suppression." (PMID 41141256, 2025). "Similarly, paeonol inhibited the M1 macrophage polarization thereby reduced serum levels of amylase, lipase, IL-1β and IL-6 and alleviated the histopathological manifestations of pancreatic tissue in a mild acute pancreatitis model." (PMID 41145464, 2025). "Interleukin-6 (IL-6) plays a complex role in acute pancreatitis." (PMID 39694959, 2024). "Furthermore, AP administration reduced the production of pancreatic TNF-α and IL-6 during cerulein-induced acute pancreatitis." (PMID 38911237, 2024). "Also, it has been stated that proinflammatory cytokines (TNFα, IL-1β, and IL-6) were significantly reduced, whereas antiinflammatory cytokines (IL-10 and IL-4) were increased in animals with acute pancreatitis pretreated with melatonin." (PMID 38333760, 2024). "Our work confirms the important role of IL-6 in acute pancreatitis and its prognostic significance." (PMID 39694959, 2024).
acute pancreatitis (continued). "Similarly, a study suggested that the levels of TNF-α, IL-1β, and IL-6 were increased in acute pancreatitis groups compared with the sham group." (PMID 38333760, 2024). "Curiously, as a result of Galunisertib treatment, a reduced serum levels of MPO, IL-1β and IL-6 were observed in the acute pancreatitis model, implying those factors could also contribute to mesenchymal activation." (PMID 38322992, 2024). "There are also studies for other inflammatory conditions, including acute pancreatitis, where targeting the IL-6 pathway may reduce excessive inflammatory response." (PMID 39407738, 2024). "Notably, IL-6 has exhibited promise in prognosticating moderate severe or severe acute pancreatitis." (PMID 39011189, 2024). "In acute pancreatitis, increased serum levels of IL-6 correlate with disease severity." (PMID 37881430, 2023). "Tocilizumab, an antibody which blocks the classical IL-6 pathway by binding to the IL-6 receptor is approved for the treatment of rheumatoid arthritis and was also tested in an animal model for the treatment of acute pancreatitis with promising results." (PMID 37881430, 2023). "Indeed, baseline severity scores, such as the Acute Physiology and Chronic Health Evaluation II, were higher in our trial than in some recent studies and plasma interleukin-6 levels were higher than previously reported in acute pancreatitis." (PMID 37259157, 2023). "Some authors reported better usefulness in assessing interleukin-6 (IL-6) serum levels in differentiating PC patients from chronic or acute pancreatitis, or recently, leukemia inhibitory factor (LIF) was reported to be a promising serum biomarker of pancreatic malignancy." (PMID 37906289, 2023). "Activation of pancreatic proteases and dysfunction of pancreatic microcirculation in acute pancreatitis stimulate granulocytes, macrophages, and vascular endothelial cells to release IL-6, TNF-α, and other cytokines that participate in the inflammatory response and immunoregulation." (PMID 35496266, 2022). "This study showed more than a 150-fold increase in IL-6 concentration in the AP patients group in comparison with the healthy subjects group, confirming that IL-6 is an essential mediator in the pathophysiology of acute pancreatitis." (PMID 35205334, 2022). "As high levels of inflammatory cytokines and ROS are crucial factors in the progression of acute pancreatitis, we examined whether EtOH/LPS increases the levels of IL-6 and ROS in AR42J cells using time course experiments." (PMID 35326169, 2022). "Amylase, IL-6, and IL-1beta levels were found to be increased in the acute pancreatitis group." (PMID 36262104, 2022). "This study aimed to identify whether interleukin-6 (IL-6) is better than C-reactive protein (CRP) for the prediction of severe acute pancreatitis (SAP), infected pancreatic necrosis (IPN), and mortality." (PMID 36467730, 2022). "Besides, the injured pancreatic acinar cells from acute pancreatitis patients also had the initial inflammatory responses to expressed cytokines such as actor interleukin-6 (IL-6)." (PMID 33824873, 2021). "PIN significantly suppresses the production of cyclooxygenase 2 (COX-2), which is essential for inflammation, but it has also been shown to inhibit tumor necrosis factor alpha (TNF-α), interleukin 1 beta (IL-1β), and interleukin 6 (IL-6) during acute pancreatitis." (PMID 33923276, 2021). "Given previous studies showing that CVB3 can cause acute pancreatitis in humans and mice, and that TNF-α and IL-6 are implicated in the development of this disease, it is likely that cytokines are also involved in virus-induced inhibition of cell proliferation." (PMID 33556114, 2021). "Hence, we proposed that PGC-1α selectively modulates NF-κB transcriptional activity by acting as a specific NF-κB repressor toward IL-6 during acute pancreatitis." (PMID 32215168, 2020).
acute pancreatitis (continued). "Another non-exclusive hypothesis could be that the liver, the main source of hepcidin production, better translates the abdominal inflammation related to acute pancreatitis, mediated by IL-1 and IL-6." (PMID 32560276, 2020). "Besides, IL-6 was always considered to participate in acute pancreatitis by facilitating neutrophils infiltration." (PMID 33118404, 2020). "In acute pancreatitis, IL-6 promotes ANO1 expression via IL-6R/STAT3 signaling." (PMID 33841132, 2020). "The early extensive systemic release of proinflammatory cytokines, such as interleukin (IL)-1 and IL-6 in patients with acute pancreatitis may give rise to SIRS." (PMID 31068202, 2019). "Our results demonstrated that i.p. injection of 400 mg/kg bw arginine induced acute pancreatitis and neutrophil infiltration in the pancreas as indicated by elevations in serum amylase, lipase, and transaminase activities, in addition the IL-6 level compared with the control." (PMID 26100532, 2015). "In addition, in our study, the positive correlation IL-6 with Ranson criteria was noted, which can confirm usefulness of IL-6 to assess acute pancreatitis severity." (PMID 25298618, 2014). "Therefore, reduction of IL-6 and inflammatory cell accumulation may inhibit glycocalyx degradation during acute pancreatitis and protect the endothelium." (PMID 40411704, 2025). "Furthermore, hsa-miR-148a could inhibit autophagy through IL-6/STAT3 axis in AP in acute pancreatitis." (PMID 32149089, 2020). "Moreover, mice lacking IL-6 had decreased acute pancreatitis associated acute lung injury and lethality." (PMID 27036317, 2016). "DCQD treatment could increase the expression of anti-inflammatory cytokines (IL-4 and IL-10) and inhibit the expression of proinflammatory cytokines (TNF-α and IL-6) to ameliorate the histopathological damage of acute pancreatitis, in which higher dose DCQD seems to have the better effect." (PMID 26199633, 2015). "This study investigated the effects of different early resuscitation fluid replenishment rates (FRRs) on inflammation (serum interleukin-6 (IL-6) and C-reactive protein (CRP), PCT and complications in patients with severe acute pancreatitis (SAP)." (PMID 40951887, 2025). "The systemic inflammatory response mediated by IL-6, IL-8, TNF-α, and other cytokines, contributes to the development of HUS in Acute Pancreatitis." (PMID 40443860, 2025). "Several other markers, including IL-6, polymorphonuclear elastase, serum amyloid A, and serum HGF, have been evaluated for their potential role in assessing acute pancreatitis severity." (PMID 39011189, 2024). "Studies have highlighted the crucial role of NF-κB activation in pancreatic acinar cells and the subsequent expression of IL-1β, IL-6, and TNF-α in the initiation and aggravation of acute pancreatitis through the recruitment of inflammatory cells." (PMID 38550755, 2024). "It has been shown that both NF-κB and NF-κB-regulated IL-1β, IL-6, and TNF-α expressions are related to the onset and exacerbation of acute pancreatitis." (PMID 38333760, 2024). "Hydroalcoholic curry leaf extract has been found to suppress IL-1β, IL-6, and TNF-α, and activate NRF2 in acute pancreatitis mice." (PMID 36671034, 2023). "An impaired neutralization of oxidative stress can result in turn in the intensification of tissue damage and the development of inflammation, which was reflected in increased IL-6 and hs-CRP concentration in the course of acute pancreatitis." (PMID 35205334, 2022). "For instance, quercetin has been reported to downregulate the expression of IL-1β, IL-6, TNF-α, NF-κB, and other pro-inflammatory cytokines, alleviating acute pancreatitis." (PMID 39280954, 2022). "Recent studies demonstrated the elevation of IL-6 and CRP in animal models of caeruline and L-arginine induced acute pancreatitis." (PMID 35927726, 2022).
acute pancreatitis (continued). "Treatment with genistein in both low and high doses effectively decreased levels of serum IL-6 and serum CRP suggesting the anti-inflammatory effect of genistein in acute pancreatitis." (PMID 35927726, 2022). "Sixty-seven patients with acute pancreatitis (AP) who were hospitalized within 48 h of onset and received serum CRP and IL-6 tests from September 2018 to September 2019 were included." (PMID 36467730, 2022). "Serum interleukin-6 (IL-6) and C-reactive protein (CRP) levels in patients with acute pancreatitis and their correlation with severity." (PMID 36467730, 2022). "HBP is critical for pancreatic necrosis response in acute pancreatitis by increasing the infiltration of M1 macrophages and promoting the secretion of inflammatory factors, such as TNF-α, IL-6, IL-1β, which can be reduced by heparin." (PMID 34895060, 2021). "Rao and Kunte measured serum IL-6, IL-8, IL-10, and C-reactive protein (CRP) levels within 24 h of admission in forty patients of clinically predicted severe acute pancreatitis (SAP)." (PMID 34349610, 2021). "Neutrophils promote inflammation by secreting proteolytic enzymes and proinflammatory cytokines (IL-1, IL-6), leading to SIRS and organ failure in severe acute pancreatitis." (PMID 35056321, 2021). "During the first phase of acute pancreatitis, cytokine pro-inflammation, as TNF (tumor necrosis factor) α, interleukins (IL-1, IL-2, IL-18, IL-6) and chemokine, oxygen radical oxidant are released." (PMID 34036463, 2021). "In the severe acute pancreatitis (SAP) model, EA decreased the level of TNF-α and IL-6 in serum but increased acetylcholine (Ach) levels in serum." (PMID 35095910, 2021). "Acute pancreatitis was enhanced in PTP1B knockout mice via increased production of inflammatory cytokines, such as IL-1β, IL-6, and TNF-α." (PMID 32760098, 2020). "In cerulein-induced acute pancreatitis, DHA suppresses IL-1β and IL-6 gene expression by inhibiting AP-1 activation." (PMID 33158207, 2020). "Over-expression of miR-9 in bone marrow-derived mesenchymal stem cells is also known to diminish the levels of IL-6, IL-1β, and TNF-α in acute pancreatitis, highlighting the critical role of miR-9 up-regulation in inhibition of inflammatory responses." (PMID 32765295, 2020). "Previous studies showed that the administration of the interleukin-1β receptor antagonist prevents a serum rise in interleukin-6 and TNF-α levels, and decreases the severity of acute pancreatitis." (PMID 28430136, 2017). "Increase of circulating pro-inflammatory cytokines is an important feature of acute pancreatitis, so in this study serum levels of TNF-α and IL-6 were determined." (PMID 28300832, 2017). "Emodin treatment significantly reduced NF-kB DNA binding activity and the serum expression levels of TNF-α, IL-6 which led to reduced pancreatic MDA and increased SOD levels in severe acute pancreatitis rat model." (PMID 26753525, 2016). "As a consequence of acute pancreatitis, apart from hyperamylasemia, elevated production of pro-inflammatory cytokines such as TNF-α, interleukin (IL)-1β and IL-6 is often a distinctive pathological parameter." (PMID 26971398, 2016). "Several signaling molecules (such as IL-1, IL-2, IL-6, PAF, substance P, TNF-α, MCP-1, and NF-κB) have been shown to play important roles in the progression of experimental acute pancreatitis." (PMID 25147563, 2014).